LCN2 (lipocalin 2)
Diseases named in the same sentence as LCN2 in open-access papers (continued):
Sharing a sentence is not in itself a finding about the gene and the disease.
Obesity (continued). "In addition, the elevated lipocalin-2 levels of SCWAT strongly augmented the observed insulin resistance in these animals, as the elevated lipocalin-2 level has been associated with obesity, insulin resistance, while deficiency has been shown to reverse these conditions." (PMID 33088930, 2020). "Therefore, Lcn2 and its downstream signaling pathways could be a potential therapeutic target for obesity." (PMID 32883997, 2020). "Lipocalin-2 (LCN2), also known as neutrophil gelatinase-associated lipocalin (NGAL), is a secretory glycoprotein, which has a pro-inflammatory action, and which is thought to be strongly involved in the metabolic and cardiovascular complications associated with obesity." (PMID 33633748, 2020). "However, the upregulation of Lcn2 may have implications other than a protective response towards obesity." (PMID 32883997, 2020). "However, the involvement of Lcn2 and its function during the progression of obesity is largely unknown." (PMID 32883997, 2020). "However, LCN2 post-prandial response is blunted in individuals with obesity." (PMID 33231171, 2020). "Furthermore, subjects with overweight or obesity lose postprandial regulation of LCN2 and this may be a new mechanism of resistance that contributes to obesity." (PMID 33231171, 2020). "LCN-2 is increased in obese individuals, which is presumed derived from increased adipose tissue and also increased expression from the liver, but may also be due to changes in skeletal homeostasis which is also altered in obesity." (PMID 31372314, 2019). "Thus, the observed early Lcn2 production may be a trigger of later progressive renal damage in obesity." (PMID 31480394, 2019). "However, genetic deficiency of LCN2 altered neither the development of diet-induced obesity, nor the ability of celastrol to promote weight loss and improve obesity-associated dyshomeostasis." (PMID 31488870, 2019). "Obesity and psoriasis were found to be strongly associated, whereas AD and LCN2 were not." (PMID 30805373, 2019). "Thus, a molecule that could regulate the production and secretion of lipocalin-2 might ameliorate the deteriorated endothelial and metabolic dysfunctions induced by obesity, and finally contribute to the amelioration of obesity-accompanied hypertension." (PMID 29731737, 2018). "Among adipokines, lipocalin-2 and fatty acid binding protein −4 (FABP-4), members of the superfamily of lipocalins, have been investigated as markers for adipose dysfunction associated with obesity and insulin resistance, and recently with coronary artery disease." (PMID 29304747, 2018). "In addition to hepcidin, lipocalin-2 production may be important in inflammation-induced obesity-related ID." (PMID 26561830, 2015). "However, the exact role of lipocalin-2 in obesity-induced insulin resistance remains controversial." (PMID 22292925, 2012). "Lipocalin-2 suppression could attenuate aging and obesity-induced insulin resistance." (PMID 22292925, 2012). "In the PPI network constructed based on these genes, LCN2, ELANE, and MMP8 processed the most nodes, indicating their key roles in the obesity-related immune network." (PMID 39609876, 2024). "Our previous studies demonstrate that LCN2 plays an inflammatory role in the WAT, liver, and hippocampus in animal models of metabolic disorders, including obesity, non-alcoholic fatty liver disease, and T2D." (PMID 38201988, 2024). "Thus, because LCN2 acts as an anorexigenic signal, the next step was to examine whether LCN2 elevation in obese mice and humans might be a compensatory mechanism to combat obesity, insulin resistance, and other metabolic dysregulations." (PMID 38035773, 2024). "The aim of the study was to determine the effects of 12-week supervised SIT on serum osteocalcin, lipocalin-2 and sclerostin levels, bone mineral density (BMD) and bone mineral content (BMC) characteristics in adolescent boys with obesity." (PMID 37238398, 2023).
Obesity (continued). "Serum LCN2 levels are higher in ob/ob, db/db, and HFD-induced obesity models and in human subjects with obesity." (PMID 35909571, 2022). "Here, we explored the protective role of lipocalin 2 (LCN2) against endoplasmic reticulum stress and cell apoptosis in gastric mucosa in patients and mice with obesity." (PMID 33637683, 2021). "Other studies have indicated that LCN2 may regulate brown adipose tissue (BAT) to enhance thermogenesis and energy expenditure, because LCN2 loss in mice resulted in compromised adaptive thermogenesis, and potentiated diet-induced obesity, dyslipidemia, fatty liver disease, and insulin resistance." (PMID 32544571, 2020). "Since obesity is associated with chronic low-grade inflammation, increase in visceral adiposity and weight gain seen in Lcn2KO mice may be partly due to the absence of Lcn2-mediated anti-inflammatory effects." (PMID 32883997, 2020). "Recent studies in human and animals have shown that both lipocalin-2 and RBP4 are modulators of insulin signaling and their levels are elevated in subjects with obesity, insulin resistance, or type 2 diabetes." (PMID 23799122, 2013). "LCN2 is a major contributor to inflammation in adipose and other tissue in HFD-induced obesity." (PMID 38201988, 2024). "However, further research is needed to better understand the role of LCN2 in neuroinflammation and BBB maintenance in obesity." (PMID 38201988, 2024). "LCN2 can cross the blood–brain barrier and activate the melanocortin four receptor (MC4R)-dependent pathway, one of the most potent regulating pathways of obesity." (PMID 37326909, 2024). "Supervised 12-week SIT intervention improved bone mineral characteristics, but did not change osteocalcin, lipocalin-2 or sclerostin levels in adolescent boys with obesity." (PMID 37238398, 2023). "Taken together, these data show that Lcn2 promotes PDAC progression and associated cachexia, though these effects are not clearly linked to obesity." (PMID 37648285, 2023). "This suggests that celastrol-mediated anti-obesity effects do not involve LCN2, and the exact mechanism remains unelucidated." (PMID 36009315, 2022). "Selenite supplementation during adolescence favored adipogenesis by promoting insulin secretion and sensitivity leading to a general anabolism, without obesity or inflammation, in which the adipokine LCN2 played a pivotal role." (PMID 36079831, 2022). "Similarly, among the 15 anti-inflammatory organokines, 7 (adiponectin, Omentin-1, ZAG, SFRP5, CTRP3, IL-10, and DEL-1) showed reduced levels and 8 (LCN2, VASPIN, IL-1RA, FGF21, GDF15, MANF, Irisin, and IL-6) showed elevated levels in patients with obesity." (PMID 35909571, 2022). "Using KrasG12D;Ela-CreERT;Lcn2−/− mice (whole body deletion of LCN2) Cruz-Monserrate and colleagues showed that lack of LCN2 prevents weight gain and obesity when fed a high-fat diet." (PMID 34680216, 2021). "Another interesting molecule that may provide a link between obesity and PDAC is lipocalin-2 (LCN2)." (PMID 34680216, 2021). "Serum LCN2 levels are postprandially increased in individuals with normal weight and overweight but not in individuals with obesity or with severe obesity." (PMID 33231171, 2020). "In human studies, LCN2 levels increased after a meal in individuals with normal weight or overweight, but not in individuals with obesity." (PMID 33231171, 2020). "We show here that meal challenges increase serum LCN2 levels in persons with normal or overweight, but not in individuals with obesity." (PMID 33231171, 2020). "Together with the normal responses of Lcn2−/− mice to HFD feeding and celastrol (above), these results illustrate that LCN2 does not play a role in the development of diet-induced obesity, or in its therapeutic reduction by celastrol." (PMID 31488870, 2019). "Lipocalin-2 was higher in obesity but only in control women; whereas in the non-obese subgroup patients with PCOS presented the largest concentrations." (PMID 31652917, 2019).
Obesity (continued). "Finally, lipocalin-2 (LCN2), an adipokine correlated with obesity and IR, has been shown to exacerbate psoriatic skin lesions in mice, through increase of IL-17A/F, IL-23p19, IL-12p40, CCL20 and TNF-α, levels, but not IL-12p35." (PMID 28708082, 2017). "Importantly, Lcn2 knockout decreased weight gain and had an impact on survival independent of HFD feeding, indicating that Lcn2 is required for tumorigenesis even in the absence of obesity." (PMID 37648285, 2023). "In addition, different studies demonstrated the anti-obesity effect of celastrol was independent on melanocortin 4 receptor (MC4R), and lipocalin 2 (Lcn2), because the deletion of these genes did not weaken the weight-loss and liver-protecting effect of celastrol in mice." (PMID 35444532, 2022). "Thus, because LCN2 plays an important role in the inflammation of adipose tissue and liver from HFD-induced obesity, we expected that ABE could reduce LCN2 protein levels in HFD-fed mice." (PMID 36501079, 2022). "However, the mechanism by which LCN2 alleviates obesity-induced gastric injury is not fully understood." (PMID 33637683, 2021). "The extent of postprandial elevation of serum LCN2 response is affected by BMI, as women with normal weight have the highest response, women with overweight have a positive yet relatively attenuated response and women with obesity have a negative response." (PMID 33231171, 2020). "However, whereas LCN2 levels inversely correlate with hunger in normal weight and overweight subjects but not obese individuals, GLP1 levels only inversely correlate with hunger scores in subjects with obesity." (PMID 33231171, 2020). "Naturally occurring elevation in Lcn2 levels seen in obese mice may not be sufficient to control or reverse the pathological changes induced by obesity." (PMID 32883997, 2020). "Meanwhile, an increase in serum levels of lipocalin-2 has been suggested as a useful biomarker with which to determine clinical responses to antihistamine treatment in CSU patients: this biomarker has also been shown to be correlated with metabolic syndrome and obesity." (PMID 31346408, 2019). "Similarly, the circulating levels of LCN2 and hepatic expression of LCN2 were significantly higher in female NAFLD patients than in women with severe obesity with non-significant liver disease, again suggesting LCN2 as a good biomarker for assessment of NAFLD." (PMID 27729871, 2016). "Nevertheless, whether lipocalin-2 plays a role in the pathogenesis of obesity-related diseases has not been investigated so far." (PMID 24741591, 2014). "However, the results from studies into the phenotype of the lipocalin-2 knockout mouse are mixed, with reports of no phenotype, as well as protection from and promotion of an obesity phenotype and insulin resistance." (PMID 24205333, 2013). "However, it is not clear whether the reduced tumor growth in KrasG12D;Ela-CreERT;Lcn2−/− mice was directly due to the lack of LCN2 effects on the pancreas or indirectly to the reduced weight gain (anti-obesity effects)." (PMID 34680216, 2021). "Moreover, using an Lcn2 whole-body knockout mouse model, it was shown that lack of Lcn2 expression reduced extracellular matrix deposition, extended survival, and delayed tumor growth in both an obesity-driven genetic and an orthotopic mouse model of pancreatic cancer." (PMID 32575507, 2020). "Thus, we conclude that LCN2 is very unlikely to be a major influence on anorexigenic and anti-obesity signaling, and does not play any role in celastrol-mediated food intake and body weight reduction, despite its increased levels in the bone marrow and plasma after celastrol treatment." (PMID 31488870, 2019). "Supportive of an obesity-specific effect, depletion of either CLDN1 or LCN2 did not affect tumor take rate in the lean mice." (PMID 35013251, 2022).
Obesity (continued). "Lcn2+/+ and Lcn2−/− DIO mice achieved an identical degree of obesity on HFD feeding before celastrol treatment, despite the fact that knockout mice did not have any detectable LCN2." (PMID 31488870, 2019). "Baseline biomarkers in 2000-4 (CRP, IL-6, sTNFR2, leptin, lipocalin 2 and A-FABP) had significantly positive correlation with indices of obesity WC and BMI while adiponectin had significant negative correlation." (PMID 24205276, 2013). "Previous studies reported that the putatively negative correlation between BMA percentile and lipocalin-2 levels and the increased BMA percentile in patients with acute AN and severe obesity, determination of the bone components may reveal the impact of diseases on lipocalin-2 secretion." (PMID 37025415, 2023).
chronic kidney disease (199 papers, 2010 to 2026). Impairment of the renal function secondary to chronic kidney damage persisting for three or more months. "This molecule belongs to the lipocalin superfamily and is involved in many functions, such as inflammation, chronic renal failure, energy metabolism, and tumor association, but the role of LCN2 in bone metabolism is still unclear." (PMID 37408474, 2023). "LCN2, a neutrophil gelatinase-associated lipocalin, is a small glycosylated protein that is regarded as a biomarker of acute kidney injury and is thought to associate with chronic kidney disease progression in humans." (PMID 30608957, 2019). "In summary, as early diagnosis of lupus nephritis lowers the risk for progression to end-stage renal disease and death, the determination of urinary lipocalin-2 levels could become a suitable biomarker for kidney function." (PMID 37189804, 2023). "Urinary neutrophil gelatinase-associated lipocalin (NGAL, LCN2) is up-regulated after tubular cell injury and may also be a marker of kidney disease and severity in chronic kidney disease, including FSGS." (PMID 26577187, 2015). "In addition, it has been implicated that Lcn-2 might also enhance the diagnosis and state of chronic renal failure." (PMID 23861783, 2013). "One study reported an increase in LCN2 in chronic kidney disease and left ventricular hypertrophy along with increased fibroblast growth factor 23 (FGF23)." (PMID 38673873, 2024). "Lipocalin 2 (Lcn2) is a secreted acute-phase protein that is highly expressed upon inflammatory stimulation during bacterial infection, heart failure, chronic kidney disease, and cancer." (PMID 37222464, 2023). "LCN-2 is a well-established biomarker for acute and chronic kidney diseases and is rapidly upregulated after renal tubular injury." (PMID 36718277, 2023). "LCN-2 is a glycoprotein whose expression is up-regulated in adipose tissue, chronic kidney disease, human bone marrow cells and heart disease." (PMID 37631238, 2023). "In diabetic chronic kidney disease, urinary lipocalin-2 levels were ~5-fold higher compared to controls." (PMID 37189804, 2023). "Decreasing FGF23 levels by inhibition of lipocalin-2 has been suggested as a therapeutic approach to improve outcomes in chronic kidney disease." (PMID 36157448, 2022). "Mouse studies have recently shown that lipocalin-2 mediates the expression of Fgf23 in osteoblasts and osteocytes in response to inflammation and in chronic kidney disease." (PMID 36157448, 2022). "Bibliographic evidence shows correlation between LCN2 and fibrosis in SSc, Chronic Hepatitis C and Chronic Kidney Disease." (PMID 33826640, 2021). "The connection between ER stress and LCN2 expression has already been described in other malignancies like prostate cancer and chronic kidney disease." (PMID 34439364, 2021). "Various studies previously identified Lcn-2 as an iron transporter that plays a pivotal role in both acute and chronic kidney disease." (PMID 33065981, 2020). "In this condition, the high concentration of LCN2 induces endoplasmic reticulum stress-induced apoptosis leading to chronic kidney disease, proteinuria and severe tubulointerstitial damage, which ultimately leads to end-stage renal disease." (PMID 27729871, 2016). "Lipocalin 2 is a biomarker for human acute kidney injury and it has been shown to play an essential role for chronic kidney disease progression in mice and humans." (PMID 24705830, 2014). "Even though Lcn-2 achieved attention as a very useful marker in acute and chronic renal failure, its function in kidney disease revealed elusive until very recently." (PMID 23861783, 2013). "Lipocalin-2 is a promising biomarker of acute kidney injury and chronic kidney diseases." (PMID 31269059, 2019).
chronic kidney disease (continued). "In this report, it was found in experimental models of chronic kidney disease in mice from different genetic backgrounds, that the severity of renal lesions was strongly dependent on LCN2 that significantly correlated with hyperproliferation and disease progression in both mice and humans." (PMID 27729871, 2016). "In addition to acute injury in the kidney, another study reported an active critical role of LCN2 activity in the formation of chronic kidney disease." (PMID 27729871, 2016). "The specific mechanism behind the continuous expression of the LCN2 gene is unclear yet, but LCN2 levels are elevated in both the acute and chronic stages of kidney injury and may be a significant role in the development of chronic kidney disease." (PMID 40171220, 2025). "Owing to the high morbidity of cardiovascular diseases (CVD) in patients with chronic kidney disease (CKD), renal biomarkers such as beta-2-microglobulin (B2M), cystatin C and lipocalin-2 (LCN-2) have attracted increasing attention." (PMID 37155257, 2023). "Although the serum, plasma and urine levels of LCN2 have been regarded as biomarkers for cardiometabolic (CMD) and chronic kidney (CKD) diseases, there are inconsistent reports on the use of this molecule as a biomarker for early diagnosis or prognosis." (PMID 34938273, 2021). "Hepatitis A virus cellular receptor 1 (Havcr1, also known as Kim-1/Tim-1) and lipocalin 2 (Lcn2, also known as Ngal) are excellent markers to predict TILs in both AKI and chronic kidney disease (CKD)." (PMID 29109726, 2017).